SCYGR1 (small cysteine and glycine repeat containing 1)
Description:
In the hair cortex, hair keratin intermediate filaments are embedded in an interfilamentous matrix, consisting of hair keratin-associated proteins (KRTAP), which are essential for the formation of a rigid and resistant hair shaft through their extensive disulfide bond cross-linking with abundant cysteine residues of hair keratins. The matrix proteins include the high-sulfur and high-glycine-tyrosine keratins.
Synonyms: KRTAP28-1
Gene: Protein-coding gene on chromosome 2 (227,387,683 to 227,387,949, reverse strand). Ensembl gene ENSG00000284629.